RNU6-34P (RNA, U6 small nuclear 34, pseudogene)
Synonyms: RNU6-34
Gene: Small nuclear RNA gene on chromosome 4 (96,152,297 to 96,152,403, reverse strand). Ensembl gene ENSG00000201744.
Homologues: Orthologues: chimpanzee U6 (98% identical), rabbit U6 (93% identical), dog U6 (84% identical), dog U6 (79% identical), guinea pig U6 (79% identical). Paralogues in human: RNU6-11P (95% identical), RNU6-33P (95% identical), RNU6-37P (95% identical), RNU6-1 (94% identical), RNU6-116P (94% identical), RNU6-2 (94% identical), RNU6-3P (94% identical), RNU6-4P (94% identical), RNU6-5P (94% identical), RNU6-698P (94% identical), RNU6-6P (94% identical), RNU6-7 (94% identical), and 1289 more.